MMP9 (matrix metallopeptidase 9)
Diseases named in the same sentence as MMP9 in open-access papers (continued):
Sharing a sentence is not in itself a finding about the gene and the disease.
cancer (continued). "These pathways are also involved in MMP-9/Neu-1 cross-talk, highlighting that transactivation of the IR is likely mediated by Neu-1 to promote signaling pathways involved in tumorigenesis, and its downregulation will likely lead to a decrease in cancer viability." (PMID 36831374, 2023). "In addition, CAFs could express MMP9 to enhance proangiogenic phenotype thereby facilitating cancer cell invasion ability in HNSCC." (PMID 37065499, 2023). "Upregulation of ErBb2 may either produce metastasis-related characteristics like angiogenesis or invasion, or it may promote curative resistance, ultimately deteriorating cancer cell metastasis and attempting distressing responses to cancer-curative MMP-9 and MMP-2 protein activities." (PMID 37845675, 2023). "Among them, MMP9 could destroy type IV collagen proteins in the extracellular matrix, which is the most abundant component of the basement membrane, so it also plays an important role in the invasion and metastasis of malignant tumors." (PMID 37851362, 2023). "Notably, MMP9 is involved in the neo-angiogenetic process in different types of cancer." (PMID 37372437, 2023). "In cancer setting, opioids may modulate MMP-9 production and then cancer progression." (PMID 36830637, 2023). "However, the precise epigenetic mechanisms underlying the gene regulation of Lipocalin 2 (LCN2), SLC22A17, and MMP9 in cancer still remain unclear." (PMID 36211450, 2022). "Notably, the overexpression of laminin and MMP-9 has also been reported in cancer cells." (PMID 35385679, 2022). "In addition, MMP-9 increased with the progression of cancer in three types of urological tumors." (PMID 35178444, 2022). "Thus, the MMP-9 enzymatic activity was intended to trigger the drug release in cancer cells." (PMID 35893800, 2022). "The results showed that MMP-9 may be used as a biomarker for pan-cancer prognosis." (PMID 35178444, 2022). "The regulation and inhibition of MMP-9 may inhibit cancer metastasis." (PMID 35723293, 2022). "Furthermore, EGF and BMP-4 cooperate to inhibit MMP-9 expression in cancer cells." (PMID 35150338, 2022). "Human chorionic gonadotropin (hCG), a hormone essential for pregnancy, is also ectopically expressed by a variety of cancers and is associated with a poor prognosis, which could induce the synthesis of MMP-2 and/or MMP-9, thereby increasing invasiveness in an MMP-dependent manner." (PMID 36230852, 2022). "Regarding the onset of cancer, LOX-1 was shown to be upregulated in different tumors and has been linked to their progression and metastasis through the upregulation of VEGF, the activation of HIF-1alpha, and the induction MMP-9/MMP-2, subsequently leading to neo-angiogenesis." (PMID 35269979, 2022). "Thus, we suggest that SNORA70E might regulate RAP1B and further regulates the expression of β‐catenin, PI3K, AKT1, mTOR, and MMP9 to exert cancer‐promoting effects." (PMID 36056690, 2022). "Additionally, G-Rh1 suppressed the mRNA expression of RhoA, ROCK1, MMP1, and MMP9 in cancer cell." (PMID 36500403, 2022). "Moreover, mechanistic studies indicated that miRNA-153 could indirectly promote the cancer cell invasion rate due to the induction of matrix metalloproteinase-9 (MMP-9) enzyme production." (PMID 35814435, 2022). "Moreover, the CB2 receptor agonist reduced MMP-9 secretion in dendritic cells, impairing their migration, which may also occur in cancer cells." (PMID 36297277, 2022). "Additionally, all four compounds have been reported to be active against cancer and other diseases, indicating strong possibilities that they could be potential hit inhibitors against MMP-9." (PMID 35463960, 2022).
cancer (continued). "Therefore, MMP-9 has both cancer promoting and inhibiting cancer effects." (PMID 36246294, 2022). "Moreover, Stat3 can activate the transcription of MMP2, MMP9, and Snail in cancer cells." (PMID 35178453, 2022). "Besides, MMP-9 also can reduce IL-2 response, which may contribute to immune evasion by cancer cells." (PMID 35586209, 2022). "Thus, for the first time, differences in the levels of 20S proteasomes, ADAM10+/ADAM17-, MMP9+ and MMP9+/MMP2+/EMMPRIN+ in plasma exosomes subpopulations between CPPs and CRCPs were revealed, thereby indicating the feasibility of using them to predict cancer risk." (PMID 33773551, 2021). "Interestingly, SCFAs can also modulate onco- and suppressor genes expression through epigenetic modifications: L. rhamnosus GG supernatant increases ZO-1 expression (responsible for intercellular permeability) and decreases MMP-9 expression that facilitates cancer cell penetration." (PMID 35010297, 2021). "With the exception of MMP-9 mRNA in OVCAR4 cells, CIS and PTX both significantly increased the expression of MMP-2, -9 and -14 mRNAs and concurrently increased the expression of three CSC markers (OCT4A, EpCAM, CD133), associated with chemoresistance in the cancer cell lines." (PMID 35047406, 2021). "Notably, cancer MMP-9 significantly correlates with depth of invasion and lymph node metastasis." (PMID 33562660, 2021). "MMP2 and MMP9 may play important roles in cancer cell migration and invasion." (PMID 34812264, 2021). "However, the humanized monoclonal MMP-9 antibody andecaliximab is in late-stage development for cancer and auto-inflammatory disorders and might improve TB outcome since the addition of an anti-MMP-9 antibody has been shown to reduce TB relapse rates in mice." (PMID 33953722, 2021). "Therefore, SMYD3 acts as an epigenetic regulator of MMP9, and consequently affects cancer invasion." (PMID 33920915, 2021). "Hence, cancer cells by skewing TAMs toward M2 phenotype promotes MMP-9 activity." (PMID 33783686, 2021). "Additionally, there are mAbs designed for MMP-2 and MMP-9 that could prove efficacious for cancer treatment." (PMID 33810259, 2021). "Moreover, COX-2 can induce CCA progression through induction of MMP-9 whereas selective COX-2 inhibitors could inhibit the cancer cell progression 62-64." (PMID 33854627, 2021). "In cancer cells, members of the MAPK family, including MEK/ERK, p38, and c-Jun N-terminal kinase (JNK), are phosphorylated and translocated from the cytoplasm to the nucleus to activate cell proliferation and regulate various downstream substrates, including MMP-2, MMP-9, and EMT-associated genes." (PMID 34733776, 2021). "MMPs (MMP2 and MMP9) were also highly expressed in the PCa samples examined in this study, suggesting that expression of MMPs is activated in PCa and may enhance cancer invasion and metastasis, providing further evidence that ANT2 plays an important role in development of PCa." (PMID 34539732, 2021). "In addition, MMP-9 can degrade E-cadherin, subsequently reduce the adhesion between cancer cells." (PMID 34789268, 2021). "Interestingly, TNF-α may interact with MMP-9, which involved in an invasion and migration of cancer cells." (PMID 33923108, 2021). "Thus, targeting the IL‐33‐macrophage‐MMP‐9 signaling may provide a generalized therapeutic paradigm for treating a broad spectrum of cancer types." (PMID 34486239, 2021). "Moreover, the FAK-SRC complex might induce MMP2 and MMP9 and subsequently increase the invasiveness of cancer cells." (PMID 34589434, 2021). "Thus, the bioactive compounds from FA and their interactions with PTGS2, HSP90, CDK6, caspase 3, Bcl-2, and MMP9 may be key in the treatment of cardiovascular disease and various cancers." (PMID 33542744, 2021).
cancer (continued). "Pro-MMP-9 is a precursor that leads to the production of a basement membrane and extracellular matrix endopeptidase degrading enzyme to promote the invasion of cancer cells into the surrounding stroma, and is often used as an index of transcriptional regulation of this gene." (PMID 32633727, 2020). "EMT, which could be activated by MMP-9 and Wnt, is crucial for cancer cell invasion and metastasis." (PMID 32267139, 2020). "Moreover, MMP-9 degrades the C1q component of the complement system: this property of MMP-9 could nullify the humoral immunity directed against cancer cells." (PMID 32630531, 2020). "Thus, our findings indicate that matrine may affect cancer invasion by down-regulation of MMP-9 and MMP-2 activities." (PMID 32630806, 2020). "Hence, it is quite probable that Aloe species might inhibit enzymatic activity of MMP-2 (72 kDa) and MMP-9 (92 kDa) in cancer-related situations." (PMID 33308217, 2020). "Among them, MMP-9, also known as gelatinase B, is one of the key proteases for the degradation of extracellular matrix and basement membrane and plays a crucial part in the occurrence and development of malignant tumors, invasion, and metastasis, as well as angiogenesis." (PMID 32698816, 2020). "Notably, cancer research has confirmed that MMP-9 triggers angiogenesis, especially VEGF." (PMID 33202817, 2020). "Therefore, targeting MMP‐2 and/or MMP‐9 might provide a strategy for cancer treatment and prevention." (PMID 32180962, 2020). "The NE and MMP9 loaded on the neutrophil extracellular traps (NETs) were also found to awaken dormant cancer cells to proliferate through sequential cleavage of laminin in the extracellular matrix of the dormant cancer cells to activate integrin and YAP signaling." (PMID 33343560, 2020). "The significantly up-regulated MMP9 gene (matrix metallopeptidase 9), one of the most widely investigated matrix metalloproteinases, is a significant protease which plays vital roles in many biological processes and cancer cell invasion, metastasis and angiogenesis." (PMID 32922167, 2020). "Additionally, Tid1 abrogates the Galectin-7/TCF3/MMP9 axis to repress the cancer metastasis." (PMID 33382817, 2020). "Although MMP-9 has been found to be a potential cancer biomarker in different types of malignancies, discovering its exact translational application value (alone or as one biomarker within a biomarker combination) in one specific cancer, still needed systematic high quality evaluations." (PMID 32944046, 2020). "The inhibition of MMP2 and MMP9 could suppress the metastasis of cancer cells." (PMID 33228670, 2020). "Neutrophil related proteases NE and MMP9 loaded on NETs’ DNA scaffolding can sequentially cleave the extracellular matrix protein laminin, which reveals an epitope to trigger proliferation of dormant cancer cells through integrin activation and FAK/ERK/YAP signaling." (PMID 33343560, 2020). "Thus, suppressing MMP‐2 and MMP‐9 can be a critical step to inhibit metastasis in cancer." (PMID 33133558, 2020). "Therefore, LOX, MMP-2, and MMP-9 are highly expressed in many malignant tumors." (PMID 31777578, 2019). "Therefore, MMP9 expression is also considered as a prognostic marker during cancer progression." (PMID 31874999, 2019). "However, which crude drug or pharmacologically active ingredient played the role in the suppression of MMP-9 and alleviation of cancer pain remains unknown." (PMID 31239855, 2019). "Inhibition of MMP-2 and MMP-9 may be a suitable therapeutic option for cancer." (PMID 31783821, 2019). "In our study, MMP-9 was associated with cancer pain, but MMP-2 was not." (PMID 31239855, 2019). "Also, MMP9 is a protein that induces cancer cell invasion and metastasis." (PMID 31874999, 2019). "However, the cancer-induced group mice had a higher level of MMP-9 compared to the normal group." (PMID 30787353, 2019). "Also, MMP9 was involved in cell invasion of many cancers including CCA." (PMID 31284679, 2019).
cancer (continued). "Interestingly, MMP9 seemed to have context-dependent roles in different cancer types." (PMID 31106200, 2019). "Moreover, an earlier study showed that Sp1 upregulates MMP2 and MMP9 in cancer cells." (PMID 30845713, 2019). "In addition, TLR4 stimulates NFκB signal transduction pathway that activates tumor promoting molecules, such as VEGF-A, cyclooxygenase 2 (COX2), interleukins IL-6 and IL-8, and MMP9, which all increase cancer cell survival, immune escape, and increased metastasis." (PMID 29478325, 2019). "Interestingly, Sp1 is also known to upregulate MMP2 and MMP9 in cancer cells." (PMID 30845713, 2019). "Therefore, it could be concluded that the simultaneous application of silver nanoparticles and cisplatin efficiently downregulated MMP-9 expression, which resulted in the reduced metastatic potential of A2780 cancer cells." (PMID 31089357, 2019). "Therefore, the expression of MMP-9 of residual cancer cells might reflect a subtype of TNBCs with more aggressive behavior, resulting in poor survival." (PMID 30241470, 2018). "In addition, it has been reported that S100A4 may support MMP-9 and MMP-13 gene expression, and also that it may enhance the activity of some MMPs, causing higher cell dissociation and cancer metastasis." (PMID 30060564, 2018). "Therefore, MMP-9 may act as the CCN6-responsive mediator, causing ECM degradation, which may lead to subsequent cancer migration and invasion activity." (PMID 30237403, 2018). "Thus, MMP-9 might play a major role in promoting cancer progression, and the evaluation of enzymes like MMP-9 may be helpful in predicting clinical outcomes." (PMID 30142200, 2018). "The relationship between the MMP-9 and TNFRSF12A needs to be proven through experimentation; however, we speculated that TNFRSF12A associated with high MMP-9 expression might accelerate cancer progression through increased angiogenesis." (PMID 30142200, 2018). "Furthermore, IL-17A was shown to promote the migration and invasion of cancer cells by up-regulating the expression of MMP-9 and down-regulating the expression of the tissue inhibitor of metalloproteinase 2 (TIMP2)—a natural inhibitor of MMPs—via the p38/NF-kB signaling pathway." (PMID 29983876, 2018). "TIMP-1 overrides MMP-9 activity in cancer and might be regulated by miR-618." (PMID 30340564, 2018). "Furthermore, our marker panel (e.g., MMP9) could have the potential utility in distinguishing low grade/low volume cancer from significant cancer." (PMID 29254211, 2017). "Therefore, MMP-9 may be the CAIX-responsive mediator that causes the degradation of the ECM, which may lead to subsequent cancer metastasis." (PMID 29137326, 2017). "Besides, only MMP2 and MMP9 were found to involve into cancer." (PMID 28427222, 2017). "Therefore, MMP-9, as one of the mediators of the CCL2/CCR2 axis interaction, may cause the inhibition of cancer cell migration and invasion." (PMID 28424406, 2017). "Thus, MMP-2 and MMP-9 have potential use for the detection of cervical lesions and cancer." (PMID 29267213, 2017). "Moreover, artemisinin reduces cancer cell migration and invasion by reducing the expression of matrix metalloprotease (MMP)-2 and MMP-9 and increases the cells’ adhesive ability by enhancing the expression of E-cadherin, resulting in the downregulation of cancer metastasis." (PMID 28737711, 2017). "Therefore, we speculate that the effects of melatonin on MMP-9 can differ depending on the stimulus and the cancer cell line." (PMID 26980735, 2016).
cancer (continued). "MMP-7 and MMP-9 are members of the matrix metalloproteinases (MMPs) family, which are extracellular proteinases that regulate basic cellular processes including survival, migration and morpho-genesis and degradation extracellular matrix during the cancer metastatic process." (PMID 26840018, 2016). "MMP-7 and MMP-9 are members of the matrix metalloproteinases (MMPs) family, which are located in extracellular and control basic cellular processes, such as morpho-genesis, migration and survival, and they can degrade extracellular matrix during the cancer metastatic process." (PMID 27166267, 2016). "Given that ubiquitin-dependent protein degradation has emerged as an important modulator of invadopodia and cancer metastasis, the identification of Rab40b-SOCS-interacting proteins might shed more light on the mechanisms that regulate MMP2 and MMP9 targeting during cancer cell invasion." (PMID 27789576, 2016). "The down regulation of MMP9 could decrease the metastatic ability of cancer cells." (PMID 26922065, 2016). "Therefore, we investigated expression of MMP-9 in CTNNA3 knockdown cells, CTNNA3 overexpression cells and control cells with and without 12-O-tetradecanoylphorbol- 13-Acetate (TPA) treatment, which is an activator of protein kinase C that can promote cancer cell invasion via MMP-9 induction." (PMID 26882563, 2016). "Thus, the dysregulation of MMP-9 and the expression of N-cadherin may be essential for promoting the aggressive invasion of carcinoma cells." (PMID 27737648, 2016). "Shedding of N-cadherin may contribute to the invasion of carcinoma cells via upregulation of MMP-9." (PMID 27737648, 2016). "Furthermore, we found that the onco-suppressive effects of Salin may partially mediate MMP9 expression via the JNK/JunD pathway, causing the suppression of cancer cell invasion and migration." (PMID 25522777, 2015). "Therefore, inhibiting the migration or invasion mediated by MMP-2, MMP-9, or u-PA could putatively provide a preventive measure against cancer metastasis." (PMID 25605016, 2015). "Moreover, in cancer patients, neutrophils expressing high levels of MMP-9 have also been found." (PMID 26819959, 2015). "Thus, we hypothesize that a signal-transduction pathway involving OPN and MMP-9, similar to that in cancer cells, may play a role in the migration of endometrial epithelial cells (EECs) in endometriotic lesions." (PMID 26289107, 2015). "Therefore, the expressional suppression of MMP-2 and MMP-9 may result in the inhibition of migration in cancer cells." (PMID 25634589, 2015). "The relevant source of MMP9 as a poor prognosis marker in human cancer remains unclear." (PMID 24811362, 2014). "Therefore, the activation of MMP-9 in cancer progression may be derived in part from its modulation by AP-1 and NF-κB transcription factors in response to extracellular stimuli." (PMID 25174454, 2014). "Thus, inhibition of MMP-9 activity could reduce inflammation and prevent cancer progression and metastasis as well." (PMID 25431779, 2014). "Therefore, in the case of MMP-9, one reason for the obvious failures of broad-spectrum and specific MMPIs in cancer treatment might be due to its fluctuating role in cancer, which not only affects carcinoma cells but also other cell populations." (PMID 23365550, 2013). "Moreover, at the molecular level, inhibition of Dicer in human cancer U251, MCF-7 and SCG7901 cell lines enhanced the expression of cell cycle-associating molecules cyclin A and PCNA, as well as invasion-promoting factors MMP-2 and MMP-9." (PMID 23599754, 2013). "The results of this study demonstrate that the expressions of MMP-9 by stromal cells and of Ki-67 by cancer cells are independent prognostic factors in canine MMTs, that may be used for the selection of those animals that should be considered for post-operative ancillary treatments." (PMID 23289974, 2013).